ICAM1 (intercellular adhesion molecule 1)
Diseases named in the same sentence as ICAM1 in open-access papers (continued):
Sharing a sentence is not in itself a finding about the gene and the disease.
influenza (continued). "Furthermore, the CD5+ B-1a cell subset, which produces natural broad specificity anti-influenza IgMs that contributes to early protection, also normally accumulated in ICAM-1/2-/- MedLNs of PR8 infected mice." (PMID 36895258, 2022). "Strikingly, the mortality rates caused by either semi-lethal or lethal doses of PR8 influenza were indistinguishable between WT and ICAM-1/2-/- mice." (PMID 36895258, 2022). "Thus, all major components of anti-viral humoral immunity are normally elicited in lung draining LNs deficient in ICAM-1 and ICAM-2 during a primary influenza infection, resulting in normal IgG dependent viral clearance." (PMID 36895258, 2022). "Nevertheless, the numbers of Vβ8.3+/CD8+ effectors recovered in total lung suspensions of I.T. infected lungs, subjected to a secondary I.T. homosubtypic PR8 influenza challenge, were higher than in the primary I.N. infection and similar for both WT and ICAM-1/2-/- mice." (PMID 36895258, 2022). "Furthermore, influenza infection augmented the expression of intercellular adhesion molecule 1 (ICAM1), vascular cell adhesion molecule 1 (VCAM-1) and E-selectin on human aortic endothelial cells (HAECs) and human umbilical vein endothelial cells (HUVECs)." (PMID 34359859, 2021). "Interestingly, ICAM-1 was also shown to regulate IAV during the early stage of infection, and ICAM-1 silencing was associated with an increase in the influenza matrix gene copy number." (PMID 35008536, 2021). "Likewise, bafilomycin A1, erythromycin, and clarithromycin were studied to impede the making of IL-1β, IL-6, IL-8, TNF-α, and intercellular adhesion molecule (ICAM)-1 in influenza and rhinovirus-modeled infections." (PMID 33937285, 2021). "Our study evaluated nasal epithelial cells differentiated from five different donors, which mounted a consistent response against influenza, with potential differential responses between individuals in antiviral response genes such as IFNλs, IL36γ, IL-1A, and ICAM-1." (PMID 30487780, 2018). "Cooperative binding of both cell-surface proteins (such as ICAM-1) and viral proteins (HA in the case of influenza) is known to play a role in the innate immune response to influenza; for example, it has been shown to be essential for NK cells to stimulate the formation of granules." (PMID 27746785, 2016). "Inflammatory response to influenza, parainfluenza, and RSV infection caused epithelial injury resulting in increased expression of cell surface receptors such as platelet-activating factor receptor (PAFr), intercellular adhesion molecule-1 (ICAM-1), which serves as bacterial receptors." (PMID 38098657, 2023). "Finally, we asked whether polyclonal anti-viral Vβ8.3+/CD8+ T cells can be generated from memory CD8+ T cells also following a secondary homosubtypic PR8 influenza challenge of ICAM-1/2-/- mice." (PMID 36895258, 2022). "Similarly, extrafollicular IgG producing plasma cells which provide an initial burst of T-dependent anti-influenza antibodies essential for early control of infection, were also recovered at similar numbers in the MedLNs of both WT and ICAM-1/2-/- mice following infection." (PMID 36895258, 2022). "Intravital staining of lung vessels following influenza infection suggested a unique compartmentalization of VCAM-1 and ICAM-1, respectively, between virus infected peribronchial vessels and lung capillaries." (PMID 36895258, 2022). "Mice selectively depleted of cDC ICAM-1 expression supported, however, normal CTL and Tfh differentiation following influenza infection, ruling out essential co-stimulatory functions of DC ICAM-1 in CD8+ and CD4+ T cell differentiation." (PMID 36895258, 2022). "To systematically dissect the roles of the two ICAMs in innate and adaptive immunity to influenza infections, we followed the course of H1N1 influenza infection in WT and in ICAM-1/2-/- mice." (PMID 36895258, 2022).
influenza (continued). "The levels of the main influenza clearing IgG subtype IgG2a, and the PR8 binding affinities of these polyclonal Abs recovered from the blood of ICAM-1/2-/- mice determined at high sera dilutions, were also normal." (PMID 36895258, 2022). "When fluorescently labeled primary human peripheral blood mononuclear cells (PBMCs) were flowed through the endothelium-lined vascular channel 24 hpi with influenza H3N2, we detected upregulation of ICAM1 and TNF in the endothelial cells by qPCR, indicating endothelial inflammation." (PMID 35396513, 2022). "Our results rule out that influenza infection elevates ICAM-1 expression on alveolar capillaries and suggests that ICAM-1 and ICAM-2 do not serve as the primary ligands for neutrophil margination at steady state conditions." (PMID 36895258, 2022). "Furthermore, using a newly developed DC specific ICAM-1 KO mouse, we found normal early Ag specific naïve CD4+ and CD8+ T cell priming by influenza expressed antigens, normal Ag stimulated CD8+ T cell binding to ICAM-1 deficient DCs and intact CD8+ lymphocyte differentiation." (PMID 36895258, 2022). "Collectively, these results indicated that DC ICAM-1 is not required for normal CD8+ T cell priming and differentiation triggered by influenza expressed antigens." (PMID 36895258, 2022). "We also assessed AT2s for CD80, CD86, and ICAM-1 expression and found that AT2s expressed ICAM-1, but not CD80 or CD86, both at homeostasis and after influenza infection." (PMID 34183650, 2021). "Notably, while alveolar capillaries in influenza-infected lungs lacked VCAM-1 expression, high surface ICAM-1 expression was detected on all capillaries." (PMID 36895258, 2022).
schizophrenia (17 papers, 2012 to 2025). A major psychotic disorder characterized by abnormalities in the perception or expression of reality. "An efflux transporter, ABCG2, was lower, while mRNAs encoding VE-cadherin and ICAM1 were higher in schizophrenia brain." (PMID 30214039, 2020). "As in the cortex in schizophrenia, here we report increased ICAM1 mRNA in the midbrain associated with neuroinflammation in schizophrenia, indicating that molecular changes in the BBB exist." (PMID 33133060, 2020). "First, it could be hypothesized that patients with schizophrenia are more susceptible to infection because they have a greater inflammatory state, with the upregulation of adhesion molecules (ICAM-1, sP-selectin) and chemokines (such as CCL2)." (PMID 40276385, 2025). "Previous research has also associated elevated levels of VCAM-1 and ICAM-1 with schizophrenia." (PMID 33602170, 2021). "ICAM1 (intercellular adhesion molecule 1) is a transmembrane glycoprotein, which belongs to the immunoglobulin superfamily, and has been reported associated with schizophrenia and Alzheimer’s disease." (PMID 22899776, 2012). "In turn, IFN- γ not only is involved in the immune response against the parasite but also promotes an increase in adhesion molecules, such as ICAM-1, which is also altered in schizophrenia." (PMID 40276385, 2025). "Some authors report an increase in ICAM-1 expression in schizophrenia and depressive disorders, including bipolar affective disorder." (PMID 36984816, 2023). "The increasing level of ICAM-1 was positively correlated with increasing PBR in patients with schizophrenia (R = 0.33, P = 0.035)." (PMID 35223927, 2022). "Elevated levels of ICAM-1, VCAM-1, CRP and SAA have been associated with coronary artery disease, cancer and psychiatric disorders including schizophrenia." (PMID 33602170, 2021). "The “high inflammation” schizophrenia subgroup had lower ABCG2 and higher ICAM1, VE-cadherin, occludin and interferon-induced transmembrane protein mRNAs compared to both “low inflammation” schizophrenia and “low inflammation” control subgroups." (PMID 30214039, 2020). "One of the most robust changes in this study was an increase in ICAM1 mRNA in schizophrenia compared to controls." (PMID 30214039, 2020). "This is similar to the elevation in cortical ICAM1 mRNA, where we localized ICAM1 to the lumen of brain endothelial cells and also identified macrophages in brain tissue in schizophrenia." (PMID 33133060, 2020). "Soluble intercellular adhesion molecule-1 (sICAM1) was measured in the plasma of 78 patients with schizophrenia/schizoaffective disorder and 73 healthy controls." (PMID 30214039, 2020). "We confirmed that brain endothelial cells are a cellular source of ICAM1 in the normal adult human brain and in the brains of people with schizophrenia." (PMID 30214039, 2020). "Further, the “high inflammation” schizophrenia subgroup had an even greater increase in ICAM1 mRNA consistent with our own and other experimental results showing that IL-1β up-regulates ICAM1 mRNA in cultured endothelial cells." (PMID 30214039, 2020). "We found that ICAM1 mRNA was increased by 123.3% in the midbrain when all schizophrenia cases were compared to controls (t = −5.25, df = 40.40, p < 0.0001)." (PMID 33133060, 2020). "One interesting study compared the expression of ICAM-1 in CNS tissue in patients with unipolar and bipolar depression, patients with schizophrenia, and healthy controls." (PMID 31824303, 2019). "ICAM-1 mRNA expression in the prefrontal cortex was compared in a “high inflammation” schizophrenia subgroup—defined a priori acording to a cluster of cortical pro-inflammatory cytokine mRNAs in the patients—a low inflammation subgroup, and healthy controls." (PMID 31824303, 2019). "CD163 and intercellular adhesion molecule 1 (ICAM1), which is responsible for peripheral immune cell recruitment, both have increased mRNA expression in the prefrontal cortex of the high inflammation subgroup in schizophrenia." (PMID 34911938, 2021).
schizophrenia (continued). "When analyzed by inflammatory subgroup, ICAM1 gene expression was increased in the high inflammatory/schizophrenia subgroup by 213.4 and 295.1% compared to the low inflammatory/schizophrenia subgroup and the control group, respectively (F = 39.84, df = 51,2, p < 0.0001, both comparisons p < 0.0001)." (PMID 33133060, 2020). "Evidence suggests that macrophages may enter the brain in schizophrenia, as increases in the vascular macrophage capture molecule, intercellular cell adhesion molecule 1 (ICAM1) and increases in CD163 mRNAs are found in the cortex and hippocampus." (PMID 33133060, 2020). "People with high levels of cytokine expression and schizophrenia display changes consistent with greater immune cell transmigration into brain via increased ICAM1, which could contribute to other neuropathological changes found in this subgroup of people." (PMID 30214039, 2020). "Elevated sICAM1 in the plasma of people with schizophrenia may reflect enhanced cleavage of membrane bound ICAM1 on the endothelium following recruitment of immune cells into the tissue." (PMID 30214039, 2020). "A recent study in schizophrenia patients estimated ICAM-1 expression in the brain." (PMID 31824303, 2019). "The molecular environment in the midbrain in schizophrenia, especially the high inflammatory cases, demonstrates changes that are consistent with increased capture and transmigration of monocytes, as indicated by the increase in ICAM1 mRNA in cases with a high inflammatory biotype." (PMID 33133060, 2020). "Changes in vascular endothelial growth factor (VEGF), intercellular adhesion molecule-1 (ICAM-1), and vascular cell adhesion molecule-1 (VCAM-1) levels have also been observed in schizophrenia patients." (PMID 39940642, 2025). "Elevated levels of soluble or membrane-bound ICAM-1 and VCAM-1 levels have been reported in the CSF or brains of individuals with schizophrenia, unipolar or bipolar depression." (PMID 36904292, 2023). "It is also supported by the positive correlations between blood-derived immune cell markers and the adhesion molecule ICAM1 in this study, and gene overexpression in the diapedesis pathway in the SEZ in schizophrenia." (PMID 34911938, 2021). "Peripheral measures of soluble ICAM1 (sICAM1) and VCAM1 have been reported to be both decreased and increased in schizophrenia dependent on the stage of illness and medication status." (PMID 30214039, 2020). "Further, ICAM1 transcript levels were correlated with CD163 mRNA in the whole cohort (r = 0.42, p = 0.001) and also in the schizophrenia (r = 0.37, p = 0.036) and control (r = 0.40, p = 0.022) groups." (PMID 30214039, 2020). "Furthermore, as an initial step towards translating our research to the clinic, we determined whether ICAM1 is elevated in the periphery by measuring its soluble form in plasma in an independent cohort of living patients with schizophrenia or schizoaffective disorder and healthy controls." (PMID 30214039, 2020). "We found CD163+ cells around blood vessels and in the parenchyma and increases in ICAM1, CD163, CD64, and FN1 mRNAs as well as increases in all complement transcripts in the midbrain of schizophrenia cases with high inflammation." (PMID 33133060, 2020). "Investigation of ICAM-1 in psychiatric disorders is relevant for two reasons: this protein plays a key part in the blood-brain barrier (BBB), is important for the pathogenesis of schizophrenia and other psychiatric disorders, and is a marker of inflammation." (PMID 36984816, 2023). "We previously reported increases in CD163 and CD64 mRNAs in schizophrenia compared to controls and bipolar disorder; however, expression of no other peripheral immune cell markers or ICAM1 differed across diagnosis." (PMID 34911938, 2021).
schizophrenia (continued). "As ICAM1 has also been reported to be highly expressed in microglia, we measured the expression of the prototypical microglia marker, IBA1 and found ICAM1 was not correlated with IBA1 mRNA in controls (r = 0.20, p = 0.30) or schizophrenia (r = 0.13, p = 0.51)." (PMID 30214039, 2020). "We did not detect a difference in ICAM1 mRNA in the low inflammatory/schizophrenia group compared to the control group (p > 0.05)." (PMID 33133060, 2020). "Here, we hypothesized that markers consistent with infiltrating macrophages (ICAM1, CD163, and FN1 mRNAs) would be increased in midbrain parenchyma near dopamine cell bodies in people with schizophrenia and a high inflammatory biotype." (PMID 33133060, 2020). "Elevated ICAM1 does not necessarily prove that the BBB is more leaky in individuals with schizophrenia, but instead supports the hypothesis that luminal walls of blood vessels have more potential for increased capture of immune cells in the disease state." (PMID 30214039, 2020). "Microglia mRNA was not altered in schizophrenia nor did it correlate with ICAM1 expression." (PMID 30214039, 2020). "We assessed previously published GFAP mRNA data in this cohort and found that ICAM1 and GFAP mRNA transcripts correlated in DLPFC from controls (r = 0.40, p = 0.04) but not from people with schizophrenia (r = 0.26, p = 0.16)." (PMID 30214039, 2020).
allergic rhinitis (16 papers, 2012 to 2024). Inflammation of the nasal mucous membranes caused by an IgE-mediated response to external allergens. "Based on their connectivity and since allergic rhinitis is frequently associated with comorbid allergic conjunctivitis (i.e., rhinoconjunctivitis), it makes sense to also envision ICAM-1/allergen-specific nanobodies formulated as eye drops in the future." (PMID 39062843, 2024). "ICAM-1 is upregulated in the nasal mucosa of allergic rhinitis patients, and HRV causes activation of epithelial cells through this receptor." (PMID 26367003, 2015). "Another study revealed that adhesion facilitates the differentiation of allergic rhinitis CD4IL4 T cells through ICAM1 and E-Selectin, leading to the production of the anti-inflammatory factor IL4." (PMID 39399526, 2024). "Recent studies have also reported that blocking ICAM1 can silence CD4IL4T cell differentiation in allergic rhinitis." (PMID 37118713, 2023). "Previous research has indicated that miR-150-5p regulates the function of lymphoid cells via the ICAM-1/p38/MAPK signaling pathway in allergic rhinitis." (PMID 36203618, 2022). "Intercellular Adhesion Molecule 1 (ICAM-1) levels in the nasal fluid of HTLV-1 carriers with allergic rhinitis were lower than those observed on uninfected allergic rhinitis controls." (PMID 22499368, 2012). "In addition, nasal epithelial curettage samples were taken for analysis of mRNA (transcriptomics) for intercellular cell adhesion molecule-1 (ICAM-1) that is elevated in the nasal mucosa in allergic rhinitis." (PMID 26367003, 2015). "Soluble intercellular adhesion molecule-1 (ICAM-1) and soluble vascular adhesion molecule-1 (VCAM-1) play important roles in allergic rhinitis (AR)." (PMID 35011854, 2021). "The targets of 48 putative therapeutic components in the treatment of allergic rhinitis include IL6, TNF, CXCL8, ICAM1, ILA, MMP9, IL10, and IL1B." (PMID 31611923, 2019). "The aim of the study was the analysis of adhesion molecules' profile (ICAM-1, VCAM-1, and E-selectin) in patients with allergic rhinitis and the influence of H1 antihistamines on those markers." (PMID 30008985, 2018). "α-Pinene, the main component of SO, decreased TNF-α, IL-1β, IL-6, intercellular adhesion molecule-1 (ICAM), and macrophage inflammatory protein-2 (MIP-2) levels, as well as eosinophil and mast cell infiltration in the nasal mucosa in an ovalbumin-sensitized allergic rhinitis mouse model." (PMID 35744988, 2022). "On the other hand, some researchers did not observe an increased level of ICAM-1 and VCAM-1 in serum of patients with allergic rhinitis." (PMID 30008985, 2018).
Alzheimer disease (16 papers, 2008 to 2025). A progressive, neurodegenerative disease characterized by loss of function and death of nerve cells in several areas of the brain leading to loss of cognitive function such as memory and language. "Aging is the main risk factor for Alzheimer’s disease (AD), and a dramatic increase in extravascular ICAM-1 (associated with GFAP-immunoreactive astrocytes) is seen in the orbitofrontal cortex in normal aging." (PMID 31824303, 2019). "Furthermore, ICAM1 expression has been reported to be associated with other diseases including Alzheimer’s Disease and cancer." (PMID 25483140, 2015). "Apart from inflammatory cytokine secretion upon stimulation, e.g., astrocytes can also express ICAM-1 in inflammatory conditions such as MS, brain injury and Alzheimer’s disease (AD)." (PMID 35488987, 2022). "Levels of natural CR3 ligands, such as complement fragments, ICAM-1, and fibrin, are also increased in Alzheimer's disease patients." (PMID 34335238, 2021). "Integrin β2 and ICAM1 are also expressed on activated microglia found in the vicinity of amyloid deposits in Alzheimer's disease." (PMID 18464936, 2008). "The cell adhesion molecules ICAM-1 and VCAM-1 have been shown to mediate leukocyte migration in aging and age-released degenerative disorders such as Alzheimer’s disease and vascular dementia." (PMID 40427506, 2025).